DDR1 (discoidin domain receptor tyrosine kinase 1)
Diseases named in the same sentence as DDR1 in open-access papers (continued):
Sharing a sentence is not in itself a finding about the gene and the disease.
tumor (continued). "Together, these findings underscore DDR1's potential as a therapeutic target in a variety of cancers, particularly in those with altered immune responses or collagen-rich tumor microenvironments." (PMID 40713963, 2025). "For example, 7rh a selective inhibitor of DDR1 has been shown strong inhibitory effects in tumor cell proliferation of breast cancer, pancreatic cancer, and gastric cancer." (PMID 40248197, 2025). "While DDR1 inhibitors primarily block its kinase activity, DDR1 degraders reduce the total protein levels of DDR1, thereby addressing its roles in both signaling and structural processes that contribute to tumor progression and immune evasion." (PMID 40713963, 2025). "The analysis of ESTIMATE scores indicates that DDR1 expression is significantly and negatively correlated with both immune infiltration and stromal components within the tumor microenvironment across multiple cancer types such as PAAD." (PMID 40869052, 2025). "This study significantly expands upon previous work by providing a more detailed and comprehensive exploration of DDR1’s role in tumor immunity and microenvironment regulation." (PMID 40869052, 2025). "Mechanistically, DDR1 sustained tumor cell survival by forming 14–3-3-mediated assembly of a DDR1/14–3-3/Akt ternary complex, thereby activating the Akt/mTORC1/SREBP1/SCD1 axis to promote monounsaturated fatty acid (MUFA) biosynthesis and suppress ferroptosis." (PMID 40993737, 2025). "Despite their selectivity, these kinase inhibitors primarily target the intracellular enzymatic domain of DDR1, which contributes to tumor proliferation." (PMID 40713963, 2025). "DDR1 plays important roles in tumorigenesis, regulating tumor cell proliferation, migration, invasion, and energy metabolic reprogramming." (PMID 41154598, 2025). "Our analysis revealed that copy number variations (CNVs) significantly influence DDR1 expression among seventeen tumor types such as PAAD, OV, and STAD." (PMID 40869052, 2025). "Overexpression of DDR1 abolished the erastin‐induced inhibition of BC growth, while ferroptosis was significantly reduced in tumour tissues, which further confirmed the inhibitory effect of DDR1 on BC ferroptosis in vivo." (PMID 40105492, 2025). "This dual role underscores DDR1’s complexity as both a structural and signaling hub in the tumor microenvironment, with implications for therapeutic targeting." (PMID 40869052, 2025). "It has been determined that the presence of tumor‐derived type III collagen is crucial for maintaining tumor dormancy in patients, as its disturbance reactivates tumor cell growth via the DDR1‐mediated STAT1 signaling pathway." (PMID 40470380, 2025). "ERBB2 (HER2), a receptor tyrosine kinase frequently dysregulated in breast and other cancers, also appears as a DDR1 interactor, suggesting a possible cooperative role between DDR1 and RTKs in promoting tumor cell proliferation and survival." (PMID 40869052, 2025). "Discoidin domain receptor 1 (DDR1), a collagen-binding receptor tyrosine kinase, plays a key role in extracellular matrix remodeling, tumor progression, and immune evasion." (PMID 40869052, 2025). "Multiple studies have demonstrated a significant clinical association between discoidin domain receptors (DDR1/DDR2) and tumor progression." (PMID 40563472, 2025). "Immunohistochemical results showed fewer CD4+ and CD8+ T cells in the core of Ddr1‐WT tumors compared to tumor margins." (PMID 38953306, 2024). "Homotrimeric collagen I increases proliferation of tumor cells through DDR1 and signaling through ITGA3 compared to heterotrimeric collagen I." (PMID 38659022, 2024). "In this study, a novel mechanism is elucidated by which DDR1 mediates the interactions between tumor cells and collagen, enhances collagen barriers, inhibits immune infiltration, promotes drug efflux, and leads to MMDR in CRC." (PMID 38953306, 2024).
tumor (continued). "Thereby the siRNA particles penetrate into tumor cells quickly due to its small size to modulate collagen barriers through silencing DDR1." (PMID 38953306, 2024). "Other collagens, such as type III collagen, induce tumor cells into dormancy via the DDR1/Signal Transducer and Activator of Transcription 1 (STAT1) signaling pathway." (PMID 39769286, 2024). "Further, HNSCC exhibits increased type III collagen levels that modulate the tumor cell dormancy cascades by inhibiting DDR1-mediated STAT1 signaling." (PMID 38994941, 2024). "This molecule presented cytotoxic and antitumor activity downregulating DDR1 in the tumor of SHI mice." (PMID 38474596, 2024). "A recent study reported that matrix-metalloprotease-cleaved type I collagen activates discoidin domain receptor 1 (DDR1)-NF-κB-p62-NRF2 signaling to promote tumor growth." (PMID 38233403, 2024). "Through HIF‐1α/RhoA/ROCK1 signaling, DDR1 promoted cytoskeleton reorganization to induce tumor metastasis." (PMID 39024501, 2024). "Col1 homotrimers can enhance capacity for proliferation, tumor growth, and resistance to gemcitabine via DDR1 and integrin α3β1, and resulted in a tumor microbiome rich in anaerobic Bacteroidales." (PMID 38167055, 2024). "Further experiments involved tumor transplantation from immunodeficient nude mice to immunocompetent C57 mice, resulting in significant tumor growth inhibition in the Ddr1‐KD group." (PMID 38953306, 2024). "Mechanistically, Col1 acts through DDR1–NF-κB–p62–NRF2 to regulate tumor growth and metabolism, a cascade that is activated by cCol1 and inhibited by iCol1." (PMID 38167055, 2024). "DDR1 expression is positively correlated with tumor stage and promotes tumor cell proliferation, migration and invasion." (PMID 38659022, 2024). "DDR1 overexpression promoted tumor growth and increased CXCL8 expression, accompanied by a robust increase in immunosuppressive neutrophils." (PMID 38388466, 2024). "Masson staining images revealed denser and more aligned collagen fibers, especially at the tumor margin, in patients with high DDR1 expression." (PMID 38953306, 2024). "It has been shown in vivo that tumor collagen alignment mediated by the DDR1 extracellular domain binding hinders the infiltration of CD4+ and CD8+ T lymphocytes." (PMID 39769286, 2024). "While actin cytoskeleton reorganization has profound influences on cell migration, morphogenesis and tumor metastasis, we intended to elucidate the effect of DDR1 on the metastatic capacity of GC cells." (PMID 39024501, 2024). "si‐NP penetrates into tumor cells quickly due to its small size thereby silencing DDR1 and regulating collagen barriers." (PMID 38953306, 2024). "Compared to PBS group, mice treated with chemotherapies (CPT‐11, SCR/SN38‐NP and In‐si/SN38‐NP) exhibited continued tumor growth, while those receiving DDR1‐silencing combined strategy (si/SN38‐NP) achieved nearly complete tumor eradication." (PMID 38953306, 2024). "Protein extraction from tumor tissues confirmed DDR1 knockdown by si/SN38‐NP, along with reduced levels of P‐gp and phosphorylated ERK, consistent with cell experiment results." (PMID 38953306, 2024). "The expression levels of DDR1 significantly increased in tumors compared to normal tissues during tumor progression, indicating that DDR1 is a promising prognostic factor for CRC." (PMID 38953306, 2024). "In 2021, Nature study showed that the discoidin domain receptor 1 (DDR1) performs a vital function in preventing immune cells in accessing the tumor site." (PMID 39567970, 2024). "Tumor cells sense the ECM through transmembrane receptors such as discoidin domain receptors (DDR1/2)." (PMID 38907027, 2024). "Mechanistically, collagen can bind to discoidin domain receptor 1 (DDR1) and promote tumor cell growth and migration." (PMID 38167055, 2024).
tumor (continued). "Here we demonstrated a novel immune regulating mechanism of cirrhotic ECM that collagen alters tumor cell through DDR1-NFκB-CXCL8 axis, which attracts immune neutrophil/NETs to repress T cell cytotoxicity." (PMID 38388466, 2024). "In this regard, we identified a cancer cell-derived collagen receptor DDR1 as a sensor of tumor-secreted collagen I, which enhances stem-like and metastatic behavior in vitro and in vivo." (PMID 38907027, 2024). "Tumor derived type III collagen sustains tumor dormancy, and its disruption restores tumor cell proliferation through DDR1-mediated STAT1 signaling." (PMID 38375034, 2024). "The immunohistochemistry (IHC) results showed that DDR1 expression positively correlated with tumor grade in GC, indicating the vital role of DDR1 in GC progression." (PMID 39024501, 2024). "DDR1 overexpression in invasive tumors confirms that the dysregulation of DDR1 enhances tumor progression." (PMID 38308500, 2024). "Among them, inhibiting the collagen receptor discoidin domain receptor-1 (DDR1) in lung cancer cells hampers tumor cell survival, leading to impaired early tumor–bone engagement during skeletal homing." (PMID 38002256, 2023). "Mechanism study revealed that EFL1 intervention enhanced the ratios of CD4+ and CD8+ and CD49b+(NK) T lymphocytes and decreased Treg cells through downregulating DDR1 in the tumor of SHI mice." (PMID 37709489, 2023). "Both pharmacological inhibition (i.e., through DDR1 inhibitor 7rh) and genetic knockout of DDR1 promoted an increase in tumor volume in a KP mouse model." (PMID 38136314, 2023). "In conclusion, DDR1 can serve as a potential therapeutic target and prognostic marker for various malignancies due to its vital role in tumorigenesis and tumor immunity." (PMID 37031216, 2023). "Pharmacological inhibition and knockout of DDR1 increased the tumor burden and altered the T-cell composition." (PMID 38136314, 2023). "DDR1 promotes tumor cell invasion and enhances the survival of tumor stem cells in a collagen‐rich environment." (PMID 38077251, 2023). "Third, the effects of DDR1 on the tumor microenvironment and immunotherapy require experimental and clinical validation." (PMID 37031216, 2023). "DDR1 expression was negatively correlated with most immune-related genes, which contribute to tumor development but was positively correlated with TAPBP30,31." (PMID 37031216, 2023). "These new collagens are the main stimulators of DDR1 tyrosine kinase receptors on the surface of tumor cells, facilitating tumor cell proliferation." (PMID 38139365, 2023). "We also assessed the relationship between DDR1 expression and DNA methylation, microsatellite instability (MSI), tumor mutation burden (TMB), and the tumor microenvironment (TME) in 33 types of cancer." (PMID 37031216, 2023). "Tumor DDR1 expression and immune infiltration were determined using western blotting, immunohistochemistry and flow cytometer methods." (PMID 37709489, 2023). "DDR1 is a collagen receptor that has a suggested role in cellular proliferation, tumor invasion, and metastasis." (PMID 37271822, 2023). "Excluding cancers without corresponding normal samples, significant differences in DDR1 expression were found between tumor and normal tissues in 17 types of cancer." (PMID 37031216, 2023). "Our results suggest that DDR1 can serve as a prognostic factor for various cancers and play a vital role in tumor immunity by influencing MSI, TMB, and tumor-infiltrating immune cells." (PMID 37031216, 2023). "Pharmacological inhibition and knockout of DDR1 increased the tumor burden, with DDR1 knockout tumors showing a decrease in CD8+ cytotoxic T cells and an increase in CD4+ helper T cells and regulatory T cells." (PMID 38136314, 2023). "DDR1 participates in tumor progression by regulating cellular functions, including migration, cytokine secretion, and extracellular matrix homeostasis/remodeling." (PMID 37031216, 2023).
tumor (continued). "HCT116 tumor cells, which were used as a positive control, showed a high expression of DDR1 compared with HOG16 cells, and incubation with collagen IV also increased the presence of the 54-kDa phosphorylated band." (PMID 36675255, 2023). "Recently, it was demonstrated that an antibody against the collagen receptor discoidin (DDR1) disrupts collagen alignment and inhibits tumor growth in TNBC." (PMID 37284199, 2023). "In summary, our first pan-cancer analyses of DDR1 indicate that this factor is differentially expressed between tumor tissues and normal tissues and reveals a correlation of DDR1 with DNA methylation and RNA methylation-related genes." (PMID 37031216, 2023). "This study investigates the impact of DDR1 on tumor burden and immune cell infiltration into the tumor microenvironment." (PMID 38136314, 2023). "DDR1 has proinflammatory and profibrotic benefits and promotes the invasion, migration and liver metastasis of tumour cells." (PMID 37007062, 2023). "In contrast, DDR1 was down-regulated in tumor tissues relative to normal tissues in kidney renal clear cell carcinoma (KIRC)." (PMID 37031216, 2023). "DDRs are receptor tyrosine kinases that bind with collagen in an integrin-independent way, and DDR1 can supplement the collagen-induced tumor progression when β1 integrin was eliminated." (PMID 36906534, 2023). "Strikingly, DDR1 KO tumors showed an increased infiltration of CD8+ T cells on the tumor core, suggesting that DDR1 is a key factor of the TME that physically restricts T cell infiltration." (PMID 37284199, 2023). "Some studies reported promoting the effect of DDR1 on cell proliferation, motility, and invasion, relying on the type of tumor and surrounding microenvironment." (PMID 37271822, 2023). "Discoidin domain receptor 1 (DDR1) has been demonstrated to be able to promote tumor invasion and metastasis and being closely related to tumor immune infiltration." (PMID 35935941, 2022). "Accordingly, ablation of DDR1 inhibited tumour growth, p65, p62, NRF2, NHE1 and SDHB expression in Col IWT pancreata but did not reduce it further in Col Ir/r pancreata." (PMID 36198801, 2022). "The clinical physiological indices shown inTable 1 demonstrated that DDR1 expression was positively correlated with tumor size, pT/N stage, vascular invasion, and clinical AJCC stage." (PMID 35593476, 2022). "This indicates that DDR1 distinguishes cleaved from intact collagens, and that the latter are capable of restraining the metabolism and growth of tumours." (PMID 36198801, 2022). "Antibodies directed against the DDR1 extracellular domain inhibited DDR1-mediated collagen fibers alignment and tumor growth." (PMID 36249782, 2022). "Here we discuss recent findings uncovering additional DDR1 functions in tumor dormancy following dissemination, immune exclusion and therapeutic resistance governed by specific TME collagen-enriched matrices." (PMID 35936735, 2022). "Patients whose tumours are enriched for iCol I and express low levels of DDR1 and NRF2 have improved median survival compared to those whose tumours have high levels of cCol I, DDR1 and NRF2." (PMID 36198801, 2022). "In accordance, tumor xenografts of high DDR1‐expressing RH36 and RMS presented low collagen content around cells." (PMID 35957513, 2022). "DDR1 or DDR2 is known to control tumor cell proliferation and invasion, depending on the tumor type and the nature of the microenvironment." (PMID 34957688, 2022). "DDR1 has been involved in tumor growth, dissemination and metastasis development, implicating an interplay between DDR1 signaling and collagen remodeling, and these functions have been extensively discussed in previous reviews." (PMID 35936735, 2022). "Surprisingly, data showed a significant decrease in DDR1 expression within tumor samples when compared with normal colon samples." (PMID 35205677, 2022).
tumor (continued). "Analysis of tumor tissue of the immunocompetent mice revealed that DDR1-KO tumors display significantly increased CD8 T cell counts." (PMID 35027528, 2022). "We found inhibition of DDR1/BCR signaling with EGFR/ERBB2 to be effective independent of KRAS mutation type and status in COAD and additional primary tumor model of GBM." (PMID 35664781, 2022). "In pancreatic ductal adenocarcinoma, pharmacological inhibition of DDR1 with a small molecule 7rh slowed the tumor progression and enhanced the therapeutic response to standard-of-care PDA regimens." (PMID 35140331, 2022). "This novel study further confirms previous results showing a function for DDR1 in tumor evasion and resistance to anti-Programmed cell Death protein 1 (PD1) immunotherapy." (PMID 35936735, 2022). "In this context, aberrant collagen deposition plays an essential role throughout this malignant process and DDR1 contributes to tumor cell responses to these collagen-enriched microenvironments." (PMID 35936735, 2022). "The positive association between the expression of DDR1 with genes SOX9, CTNNB1, or VANGL2 emphasizes its role in stemness and tumor aggressivity." (PMID 35664781, 2022). "Some studies demonstrate that DDR1 promotes tumor progression, such as tumor cells migration, invasion, and metastasis." (PMID 35140331, 2022). "Any imbalance of DDR1 leads to atherosclerosis, fibrosis, temporomandibular joint disorder osteoarthritis, and tumor." (PMID 35267698, 2022). "Studies have shown that extracellular matrix remodeling can regulate pathways such as integrin-mediated signaling, TGF-β/STAT3 signaling, and DDR1/STAT3 signaling to activate multiple signaling pathways to promote tumor survival and proliferation." (PMID 36424540, 2022). "In summary, these new studies confirm an important function of DDR1 in tumor adaptation to therapy, which implicates TME ECM remodeling." (PMID 35936735, 2022). "The significant correlation between DDR1 and regulatory T cells and T-cell exhaustion markers such as TGFβ1, PD-1, and CTLA-4 indicated that DDR1 was involved in immune escape and tumor invasion." (PMID 35935941, 2022). "It is proposed that the activity of DDR1 can promote β-catenin oncogenic activity to sustain tumor cell migration, survival, and renewal." (PMID 35805033, 2022). "Perhaps this is due to high concentrations of cCol I in the PDAC tumour microenvironment and the stronger NF-κB-activating capacity of DDR1 relative to other RTKs." (PMID 36198801, 2022). "For instance, DDR1 promotes local invasion of epithelial cancer cells into collagen fibers deposited at the front of the tumor, both in a single or collective mode." (PMID 35936735, 2022). "The treatment with the tumor soil loosening agent combined with the PD1 inhibitor significantly decreased the expression of DDR1, HIF-1α, MMP-14, and α-SMA." (PMID 36382024, 2022). "These key findings implicate DDR1 as a major contributor to tumor initiation, growth, and metastasis." (PMID 35593476, 2022). "While transcriptomic analysis were not very insightful, functional rescue assays uncovered an unsuspected mechanism behind this new DDR1 tumor function." (PMID 35936735, 2022). "Here, we review new DDR1 functions in tumor dormancy following dissemination, immune exclusion and therapeutic resistance induced by stromal collagens deposition." (PMID 35936735, 2022). "Depletion of ARF6 partially abolished tumor cells migration, invasion and metastasis driven by DDR1 overexpression with collagen I." (PMID 35140331, 2022). "Statistically, Pearson’s r correlation analysis indicated a positive association between DDR1 and CXCL5 level in 3 cases of pancreatic patient tumor specimens (case 1: r = 0.4423; case 2: r = 0.4467; and case 3: r = 0.4166)." (PMID 34237033, 2021). "Scoring from 82 tumor samples identified a positive correlation between DDR1 expression and CXCL5 production (Pearson’s r = 0.4460; 95% CI, 0.2535–0.6045) and Ly6G+ TAN infiltration (r = 0.2840; 95% CI, 0.07144–0.4720)." (PMID 34237033, 2021).